SNRPD1 (small nuclear ribonucleoprotein D1 polypeptide)
Description:
Plays a role in pre-mRNA splicing as a core component of the spliceosomal U1, U2, U4 and U5 small nuclear ribonucleoproteins (snRNPs), the building blocks of the spliceosome. Component of both the pre-catalytic spliceosome B complex and activated spliceosome C complexes. As a component of the minor spliceosome, involved in the splicing of U12-type introns in pre-mRNAs. May act as a charged protein scaffold to promote snRNP assembly or strengthen snRNP-snRNP interactions through non-specific electrostatic contacts with RNA.
Synonyms: Sm-D1; HsT2456; SMD1; SNRPD
Tractability: Small molecule: a structure with a bound ligand is known. PROTAC: UniProt records ubiquitination sites on it; ubiquitination databases record sites on it; its protein half-life has been measured.
Gene: Protein-coding gene on chromosome 18 (21,612,314 to 21,633,524, forward strand). Ensembl gene ENSG00000167088.
Subcellular location: Cytoplasm, cytosol; Nucleus
Pathways (Reactome):
Metabolism of RNA: mRNA Polyadenylation; mRNA Splicing - Major Pathway; mRNA Splicing - Minor Pathway; snRNP Assembly
Disease: Dengue Virus-Host Interactions; SARS-CoV-2 modulates host translation machinery
Chromatin organization: CHD1 and CHD2 subfamily
Gene Ontology:
Molecular function: protein binding; RNA binding; U1 snRNP binding
Biological process: mRNA splicing, via spliceosome; spliceosomal snRNP assembly; 7-methylguanosine cap hypermethylation; negative regulation of mRNA splicing, via spliceosome; RNA splicing; spliceosomal complex assembly; spliceosomal tri-snRNP complex assembly; spliceosome conformational change to release U4 (or U4atac) and U1 (or U11); U2-type prespliceosome assembly; RNA processing
Cellular component: catalytic step 2 spliceosome; cytosol; methylosome; nucleus; pICln-Sm protein complex; post-mRNA release spliceosomal complex; post-spliceosomal complex; precatalytic spliceosome; SMN-Sm protein complex; spliceosomal complex; U1 snRNP; U11/U12 snRNP; U12-type catalytic step 2 spliceosome; U12-type precatalytic spliceosome; U12-type spliceosomal complex; U2-type catalytic step 1 spliceosome; U2-type catalytic step 2 spliceosome; U2-type precatalytic spliceosome; U2-type spliceosomal complex; U4 snRNP; U4/U6 x U5 tri-snRNP complex; commitment complex; nucleoplasm; small nuclear ribonucleoprotein complex; spliceosomal tri-snRNP complex; and 6 more
Genetic constraint (gnomAD): Loss-of-function variants: 0 observed, 2.32 expected, observed/expected ratio (o/e) 0, 90% interval 0 to 1.22. That is too few expected variants to judge how well the gene tolerates losing a copy. Missense variants: 7 observed, 26.44 expected, observed/expected ratio (o/e) 0.26, 90% interval 0.15 to 0.5. Synonymous variants: 6 observed, 8.26 expected, observed/expected ratio (o/e) 0.73, 90% interval 0.4 to 1.42.
Homologues: Orthologues: guinea pig SNRPD1 (100% identical), mouse Snrpd1 (100% identical), pig SNRPD1 (100% identical), rabbit SNRPD1 (100% identical), rat Snrpd1 (100% identical), zebrafish snrpd1 (97% identical), macaque SNRPD1 (97% identical), chimpanzee SNRPD1 (92% identical), dog SNRPD1 (82% identical), Drosophila melanogaster SmD1 (82% identical), tropical clawed frog snrpd1 (79% identical), Caenorhabditis elegans F40F8.11 (34% identical). Paralogues in human: SNRPD3 (34% identical), LSM4 (29% identical).